MAP3K15 (mitogen-activated protein kinase kinase kinase 15)
Description:
Serine/threonine kinase which acts as a component of the MAP kinase signal transduction pathway. Once activated, acts as an upstream activator of the p38 MAPK signal transduction cascade through the phosphorylation and activation of several MAP kinase kinases. May function in a signal transduction pathway that is activated by various cell stresses and leads to apoptosis. Involved in phosphorylation of WNK4 in response to osmotic stress or hypotonic low-chloride stimulation via the p38 MAPK signal transduction cascade.
Synonyms: ASK3; bA723P2.3; FLJ16518
Tractability: Small molecule: a high-quality ligand is known; it belongs to a druggable protein family. PROTAC: ubiquitination databases record sites on it; a small molecule that binds it is known.
Target class: STE protein kinase ASK; Kinase; Enzyme; STE protein kinase STE11 family; STE protein kinase group; Protein Kinase
Gene: Protein-coding gene on chromosome X (19,360,056 to 19,515,508, reverse strand). Ensembl gene ENSG00000180815.
Subcellular location (Human Protein Atlas): Vesicles
Gene Ontology:
Molecular function: MAP kinase kinase kinase activity; protein serine kinase activity; ATP binding; protein kinase activity
Biological process: JNK cascade; p38MAPK cascade; MAPK cascade
Homologues: Orthologues: macaque MAP3K15 (98% identical), pig MAP3K15 (90% identical), chimpanzee MAP3K15 (89% identical), dog MAP3K15 (88% identical), mouse Map3k15 (87% identical), rat Map3k15 (86% identical), rabbit MAP3K15 (81% identical), tropical clawed frog map3k15 (76% identical), zebrafish map3k15 (71% identical), guinea pig MAP3K15 (55% identical), Drosophila melanogaster Ask1 (42% identical), Caenorhabditis elegans nsy-1 (39% identical). Paralogues in human: MAP3K5 (58% identical), MAP3K6 (44% identical).
Diseases named in the same sentence as MAP3K15 in open-access papers:
MAP3K15 is named in the same sentence as 31 diseases in open-access papers, as found by Europe PMC text mining. Sharing a sentence is not in itself a finding about the gene and the disease. The quoted sentences say what the papers report.
diabetes (5 papers, 2018 to 2024). "Together, our results suggest that loss of function of MAP3K15 protects against diabetes, but future functional studies will help fully dissect the mechanism of these PTVs." (PMID 36383675, 2022). "Using our previously developed gene-level collapsing framework, we identified that hemizygous protein-truncating variants (PTVs) in the X chromosome gene MAP3K15 conferred 35% reduced odds of developing diabetes." (PMID 36383675, 2022). "The association between MAP3K15 and reduced odds of diabetes corroborates our previous findings based on a smaller subset of 269,171 European UKB participants." (PMID 36383675, 2022). "With the addition of 150,000 more exomes in the present study, we now observe that loss of MAP3K15 is associated with a statistically significant reduced risk of diabetes diagnosis in addition to reduced HbA1c." (PMID 36383675, 2022). "Among the various forms of diabetes, the identified MAP3K15 variants were most significantly protective against T2DM (non–insulin-dependent diabetes)." (PMID 36383675, 2022). "While PTVs in MAP3K15 seem to associate with protection from diabetes broadly, a notable exception was in Admixed American individuals in MCPS who carried the well-known SLC16A11 risk haplotype." (PMID 36383675, 2022). "Nonetheless, the effect sizes for diabetes risk, HbA1c, and metformin use in hemizygous MAP3K15 PTV carriers compared to heterozygous carriers demonstrate that the protective effect of MAP3K15 loss is dose dependent." (PMID 36383675, 2022). "Under the recessive collapsing model, the ORs for the association between MAP3K15 and diabetes were consistently in the protective direction for each ancestry." (PMID 36383675, 2022). "While Mantis-ML does not distinguish between disease-causing and disease-protective effects, these results provide strong evidence that MAP3K15 is associated with diabetes-related biology." (PMID 36383675, 2022). "We discovered several risk-increasing associations with traits related to liver disease, eye disease and cancer, among others, as well as risk-lowering associations for hypertension (SLC9A3R2), diabetes (MAP3K15, FAM234A) and asthma (SLC27A3)." (PMID 34662886, 2021). "We also tested whether MAP3K15 was predicted to be associated with diabetes or diabetes-related phenotypes using Mantis-ML." (PMID 36383675, 2022). "Thus, populations of European ancestry are most adequately powered for the detection of the protective association between MAP3K15 and diabetes." (PMID 36383675, 2022). "In this expanded pan-ancestry analysis, the protective association between recessive nonsynonymous variants in MAP3K15 and diabetes increased in significance compared to that in the UKB pan-ancestry analysis (CMH OR = 0.73, 95% CI: [0.66, 0.80], P = 1.4 × 10−10)." (PMID 36383675, 2022). "In addition to performing pan-ancestry analysis in the UKB cohort, we evaluated the association between MAP3K15 and diabetes in 96,811 exomes from unrelated individuals of Admixed American ancestry in the MCPS." (PMID 36383675, 2022). "We thus sought to confirm whether the protective association between MAP3K15 and diabetes was replicated in FinnGen (release 6), which includes genotype data for 260,405 individuals of Finnish descent." (PMID 36383675, 2022). "We next tested whether the MAP3K15 association, as well as the other gene-level diabetes associations, was shared across individuals of African (n = 7412), East Asian (n = 2209), and South Asian (n = 8078) ancestry in the UKB." (PMID 36383675, 2022). "With evidence that loss of MAP3K15 may be protective against diabetes, targeting MAP3K15 could become an approach for managing diabetes." (PMID 36383675, 2022). "No adverse phenotypes were associated with protein-truncating MAP3K15 variants in the UKB, supporting this gene as a therapeutic target for diabetes." (PMID 36383675, 2022).
diabetes (continued). "We found that recessive PTVs in MAP3K15 reduce the odds of developing diabetes by 35% and significantly decrease HbA1c and blood glucose." (PMID 36383675, 2022). "Across all three pathologic lines, MAP3K15 was the most significantly up-regulated gene, strongly implicating increased MAP3K15 activity in the pathophysiology of diabetes." (PMID 36383675, 2022). "Given the notable up-regulation of MAP3K15 in cellular models of MODY, these models could offer valuable insight into MAP3K15’s role in diabetes." (PMID 36383675, 2022). "Nonetheless, our results suggest that pharmacologically targeting MAP3K15 could be an orthogonal approach to managing diabetes outside the traditional arsenal." (PMID 36383675, 2022). "These provide important clues regarding the otherwise unknown pathways that mediate the protective effect between MAP3K15 and diabetes." (PMID 36383675, 2022). "Evidence derived from two in silico tools further supports the role of MAP3K15 in diabetes." (PMID 36383675, 2022). "For individuals harboring pathogenic variants in SLC16A11, the resulting consequences in lipid metabolism may drive their likelihood of developing diabetes much more so than any effect MAP3K15 may have on glucose uptake or gluconeogenesis." (PMID 36383675, 2022). "As PTVs in MAP3K15 are strongly associated with lower odds of developing T1DM and T2DM, targeting it may have therapeutic value across the spectrum of diabetes." (PMID 36383675, 2022). "A large human genetics study finds that inhibiting the gene MAP3K15 could protect individuals from diabetes." (PMID 36383675, 2022). "MAP3K15 association with LBD risk in females is likely independent of the diabetes association." (PMID 38378815, 2024). "To further explore whether the effect of MAP3K15 on diabetes is independent of obesity, we evaluated whether European individuals with a loss of MAP3K15 are at a lower risk of developing diabetes even after adjusting for BMI." (PMID 36383675, 2022). "To further explore how MAP3K15 may contribute to the pathophysiology of diabetes in pancreatic tissue, we examined its expression in transcriptomic data collected from pancreatic cell lines harboring mutations in Nkx6-1, a gene tightly associated with maturity-onset diabetes of the young (MODY)." (PMID 36383675, 2022). "Therapeutically, this suggests that targeting MAP3K15 may influence the pathophysiology underlying diabetes rather than only reducing blood glucose." (PMID 36383675, 2022).
type 2 diabetes (3 papers, 2021 to 2024). "Separately, we identified a Finnish-enriched MAP3K15 protein-truncating variant associated with decreased odds of both type 1 and type 2 diabetes (P < 0.05) in FinnGen." (PMID 36383675, 2022). "Finally, the fourth novel association was between MAP3K15 and protection from type-2 diabetes, which is discussed in greater detail below." (PMID 34662886, 2021). "Although the MAP3K15 gene has not been reported to be associated with neurodegenerative disorders, it has recently been described in a large-scale type 2 diabetes analysis based on a cohort of 454,787 participants from the UK22." (PMID 38378815, 2024). "Although obesity is generally a central driver of type 2 diabetes, we find that the protective effects of MAP3K15 loss are notably independent of BMI." (PMID 36383675, 2022).
Hypertension (2 papers, 2021 to 2022). The presence of chronic increased pressure in the systemic arterial system. "Prior work observed that knocking out Map3k15 in mice led to increased blood pressure, but our extensive human study found that MAP3K15 PTVs appear to provide a protective effect against hypertension." (PMID 36383675, 2022). "The Finnish-enriched MAP3K15 PTV (Arg1122*; rs140104197), which is associated strongly with T1DM and T2DM, was protective against hypertension in the independent FinnGen cohort (OR = 0.85, P = 0.016)." (PMID 36383675, 2022).
viral infection (2 papers, 2023 to 2025). "The results showed that SDK1 treatment attenuated the virus infection-induced interaction of MAP3K15 with Dorsal when total protein was used for IP assays." (PMID 40749022, 2025). "The results showed that the binding of STAT to ie genes (wsv249, wsv100, wsv051, wsv403, wsv304, wsv107, wsv069, wsv083) existed during viral infection and all of them were inhibited by MAP3K15 knockdown except wsv083." (PMID 40749022, 2025). "This study elucidates the molecular mechanism by which MAP3K15 promotes viral infection." (PMID 40749022, 2025). "Immunofluorescence co-localization and in vivo Co-IP assays revealed that the interaction between MAP3K15 and Dorsal was detected only in the WSSV-infected group, but not in the normal controls, suggesting that this interaction is induced by viral infection." (PMID 40749022, 2025). "While multiple MAPK kinase kinases (MAP3Ks) play a crucial role in the step wise transmission of MAPK signals in response to the pathogen infection, little is known about the function of MAP3K15 (also known as apoptosis signal-regulated kinase 3, ASK3) in viral infection." (PMID 40749022, 2025).
breast carcinoma (1 paper, 2022).
Cirrhosis (1 paper, 2022). A chronic disorder of the liver in which liver tissue becomes scarred and is partially replaced by regenerative nodules and fibrotic tissue resulting in loss of liver function. "Gender, the stage of BCLC, status of cirrhosis, and MAP3K15 were incorporated into the nomogram for RFS." (PMID 35311629, 2022).
Hyperglycemia (1 paper, 2022). An increased concentration of glucose in the blood. "Exactly how the loss of MAP3K15 may influence insulin signaling and hyperglycemia is still unclear." (PMID 36383675, 2022).
hyperinsulinemic hypoglycemia (1 paper, 2022). An inherited autosomal recessive syndrome characterized by the disorganized formation of new islets in the pancreas and congenital hyperinsulinism. "Among the top 1% of predicted gene-phenotype relationships for MAP3K15 were “diazoxide-resistant diffuse hyperinsulinism” and “hyperinsulinemic hypoglycemia”." (PMID 36383675, 2022).
liver cancer (1 paper, 2022). An epithelial or non-epithelial malignant neoplasm that arises from the liver. "Furthermore, MAP3K15 was associated with liver cancer subclasses, tumorigenesis, cell cycle dynamics, tumor angiogenesis, the progression of liver cancer, and increased rates of recurrence of liver cancer." (PMID 35311629, 2022).
MODY (1 paper, 2022). "Understanding how MAP3K15 contributes to MODY will be an important avenue for future work." (PMID 36383675, 2022).
Nephropathy (1 paper, 2022). A nonspecific term referring to disease or damage of the kidneys. "Loss of MAP3K15 correlates consistently with lower blood glucose and HbA1c levels, which are predictive measures of microvascular sequelae such as peripheral neuropathy, nephropathy, and retinopathy." (PMID 36383675, 2022).
Obesity (1 paper, 2022). Accumulation of substantial excess body fat. "As MAP3K15 encodes a member of the mitogen-activated protein kinase (MAPK) family of signal transducers, we considered whether the protective effects of MAP3K15 loss of function may be isolated from the upstream consequences of obesity on cell signaling." (PMID 36383675, 2022).
pituitary deficiency (1 paper, 2019). "We identified CBX2 regulated genes associated with polycystic ovary syndrome (PCOS) such as TGFβ, MAP3K15 and DKK1, as well as genes implicated in premature ovarian failure (POF) (i.e. POF1B, BMP15 and HOXA13) and the pituitary deficiency (i.e. LHX4 and KISS1)." (PMID 31745224, 2019).
tumor (6 papers, 2016 to 2024). "Additionally, a loss-of-function mutation in MAP3K15 has been identified, which is thought to promote tumor cell survival by preventing apoptosis." (PMID 39372871, 2024). "In this investigation, it was observed that MAP3K1, MAP3K3, MAP3K5, MAP3K10, and MAP3K15 were upregulated in HCC tumor tissues, whereas MAP3K7, MAP3K8, MAP3K9, and MAP3K11 were downregulated in tumor tissues in GSE14520." (PMID 35311629, 2022). "The levels of AFP, the stage of BCLC, status of Cirrhosis, tumor size, levels of MAP3K13, and levels of MAP3K15 were incorporated into a nomogram for a visual representation of OS." (PMID 35311629, 2022). "Although not as effective as BCLC, we did find that MAP3K13 and MAP3K15 were better than AFP and tumor size in predicting prognosis." (PMID 35311629, 2022).
cancer (4 papers, 2020 to 2025). A tumor composed of atypical neoplastic, often pleomorphic cells that invade other tissues. "Results of GSEA revealed that low levels of expression of MAP3K13 and MAP3K15 were involved in dynamics underlying cancer development, and these were essentially consistent with the results of our own study." (PMID 35311629, 2022).
cardiovascular disease (1 paper, 2022). "We did not observe any adverse phenotypic associations (P < 1 × 10−4), including coronary artery or cardiovascular disease, in individuals with loss of MAP3K15 (“ptv,” “ptv5pcnt,” and “rec” collapsing models)." (PMID 36383675, 2022).
MAP3K15 also shares sentences with these, for which no sentence is quoted: kidney disease (2 papers); Alzheimer disease (1); asthma (1); hyperinsulinism (1); Infertility (1); Insulin resistance (1); insulin-dependent diabetes (1); liver disease (1); melanocytic nevus (1); metabolic syndrome (1); neurodegenerative disease (1); peripheral neuropathy (1); polycystic ovary syndrome (1); premature ovarian failure (1); retinopathy (1).